FGF10 (fibroblast growth factor 10)
Diseases named in the same sentence as FGF10 in open-access papers (continued):
Sharing a sentence is not in itself a finding about the gene and the disease.
colorectal cancer (2 papers, 2019 to 2021). A primary or metastatic malignant neoplasm that affects the colon or rectum. "In conclusion, our results in stage and positive lymph invasion of CRC suggest the possible role of FGF-10 in a subtype of colorectal cancer; however, this view should be confirmed by additional molecular studies with a larger sample size." (PMID 31611737, 2019). "Taken together, this study proposes that FGF-10 is a critical marker for colorectal cancer targeted therapy." (PMID 31611737, 2019). "Therefore, in this study we attempted to investigate the FGF-10 as an EMT inducer in colorectal cancer prognosis based on pathological characteristics of the tumor." (PMID 31611737, 2019). "The high expression of FGF10 is found to be correlated with the size of the CRC tumors, indicating its critical role in the prognosis and survival of colorectal cancer patients." (PMID 34790220, 2021). "Our result, i.e. overexpression of FGF-10 gene in more than 50 % of all tumors in stage III and in 50 % of all positive lymph invasion patients, reflects the importance of this factor in both progression and targeted therapy of colorectal cancer." (PMID 31611737, 2019). "Our results showed upregulation of FGF-10 gene expression in 52.1 % of all tumors in stage III, suggesting that FGF-10 might be a decisive factor in a subset of colorectal cancer tumors." (PMID 31611737, 2019).
cutaneous squamous cell carcinoma (2 papers, 2018 to 2025). "Whilst local elevation of FGF22, FGF7, and FGF10 are required for efficient healing of skin lesions, sustained elevation of FGF10 has also been implicated in cutaneous squamous cell carcinoma (SCC)." (PMID 30405704, 2018). "For example, there is evidence that loss of the tumor-suppressing lipid phosphatase PTEN and, thereby, induced autocrine FGF10/FGFR2 signaling may support the development of cutaneous squamous cell carcinoma (SCC)." (PMID 40724880, 2025).
deafness (2 papers, 2015 to 2023). An inherited or acquired condition characterized by the complete loss of the ability to hear from one or both ears. "In addition to FGF3, mutations in the FGF10 and FGFR2b have been associated with a syndromic form of deafness known as lacrimo‐auriculo‐dento‐digital (LADD) syndrome (OMIM 149730)." (PMID 36934406, 2023).
dry eye (2 papers, 2011 to 2023). "FGF10 upregulates the expression of mucin in conjunctival epithelial cells, protects the ocular surface in the rabbit dry eye model, and controls epithelial cell migration during embryonic eyelid closure." (PMID 36715672, 2023). "In this study, we have characterized the potential of FGF10 as a treatment for dry eye." (PMID 36715672, 2023). "Our finding that FGF10 injections into LGs also reduced immune cell infiltration suggests that it might mitigate the inflammatory response that is often characteristic of dry eye." (PMID 36715672, 2023). "Nevertheless, since there is no similar report yet on the effect of FGF10 in Cj-ECs, our results indicate a potential for FGF10 in treating ocular surface diseases such as dry eye, ocular surface injury, inflammation, and others." (PMID 22065934, 2011). "We have not explored the effect of FGF10 on the proliferation of corneal epithelial cells during chronic inflammation in vivo because the efficiency of FGF10 in promoting corneal epithelial healing in the rabbit model of dry eye has been previously evaluated." (PMID 36715672, 2023).
duodenal atresia (2 papers, 2017 to 2020). Duodenal atresia is an embryopathy of the cranial intestine that leads to a complete absence of the duodenal lumen. "Mutations in the endodermal Fgfr2IIIb gene or its encoding ligand Fgf10 have been found to result in both colonic and duodenal atresias." (PMID 28796978, 2017). "Based on the currently available literature regarding Fgf10-Fgfr2b signaling in duodenal atresia, we hypothesize that the etiology of DA in humans is genetically driven, and that the causative genetic changes are downstream of Fgf10-Fgfr2b." (PMID 32210824, 2020). "Coordinated RNA sequencing, validation, and protein interaction analyses are planned, focusing on the duodenum of CRISPR-derived Fgf10 knockout mice with and without duodenal atresia, as well as additional wildtype controls." (PMID 32210824, 2020).
Esophageal atresia (2 papers, 2018 to 2023). A developmental defect resulting in complete obliteration of the lumen of the esophagus such that the esophagus ends in a blind pouch rather than connecting to the stomach. "A previous study showed that lung hypoplasia with esophageal atresia was caused by downregulating FGF10 signaling in vivo." (PMID 36717779, 2023). "Given the recognized association between DA and esophageal atresia in humans, DA-affected Fgf10 null embryos were analyzed for esophageal continuity." (PMID 30473704, 2018).
gastric adenocarcinoma (2 papers, 2018 to 2019). "FGF10 is correlated to GC cell invasion and has been suggested as a prognostic biomarker and potential drug target in gastric adenocarcinoma." (PMID 31242658, 2019). "At the genetic level, amplification of FGF genes may lead to their overproduction in GC, specifically, FGF10 amplification has been reported in 3% of GC and in 5.7% of gastric adenocarcinomas." (PMID 31242658, 2019). "Interrogation of most recent cBioPortal data suggests this could be an underestimate, with FGF10 amplifications reported in 5.7% of stomach adenocarcinoma cases." (PMID 30405704, 2018).
influenza (2 papers, 2020 to 2021). An acute viral infection of the respiratory tract, occurring in isolated cases, in epidemics, or in pandemics; it is caused by serologically different strains of viruses (influenzaviruses) designated A, B, and C, has a 3-day incubation period, and usually lasts for 3 to 10 days. "Treatment of these cells with Fgf10 indorsed the renewal of the epithelial cells after tissue injury caused by influenza infection." (PMID 35076456, 2021).
lung agenesis (2 papers, 2012 to 2023). "Among others, the central role of Fgf10 has been demonstrated: it has been reported to be responsible for epithelial proliferation, and null mutants of Fgf10 or of its receptor Fgfr2b have been reported to present lung agenesis." (PMID 22615846, 2012).
metabolic syndrome (2 papers, 2019 to 2025). A cluster of metabolic risk factors for CARDIOVASCULAR DISEASES and TYPE 2 DIABETES MELLITUS. "The exogenous supplementation of FGF10 has been shown to prevent the formation and development of numerous diseases, including wound healing deficits, cardiovascular diseases, metabolism syndrome, and acute kidney injury." (PMID 31680984, 2019).
mucositis (2 papers, 2009 to 2019). Mucositis is inflammation and damage of the mucous membranes lining the mouth and other parts of the gastrointestinal (GI) tract. "FGF10, under the drug name Repifermin, failed to prove efficacy in clinical trials for wound healing, mucositis, and ulcerative colitis, though it had highly protective and therapeutic effects in animal models." (PMID 30930931, 2019).
pancreatic ductal adenocarcinoma (2 papers, 2008 to 2018). An infiltrating adenocarcinoma that arises from the epithelial cells of the pancreas. "Chronic stimulation of epithelial cells with paracrine Fibroblast Growth Factor 10 (FGF10) has been implicated in multiple cancers, including breast, prostate and pancreatic ductal adenocarcinoma." (PMID 30405704, 2018).
papilloma (2 papers, 2012 to 2018). A benign epithelial neoplasm that projects above the surrounding epithelial surface and consists of villous or arborescent outgrowths of fibrovascular stroma. "The specific contribution of FGF10 to carcinogenesis was demonstrated by induction of constitutive epidermal FGF10 expression, which produced epidermal hyperplasia and spontaneous papillomas in all mice by 3 weeks of age." (PMID 30405704, 2018). "Therefore we hypothesised that in fgf22 knockout mice, where FGF7 and/or FGF10 do not have to compete with FGF22 for receptor binding, it may allow stronger FGF-mediated cytoprotective signalling and, consequently, reduced papilloma formation." (PMID 22737238, 2012).
Peri-Implantitis (2 papers, 2025). An inflammatory process with loss of supporting bone in the tissues surrounding functioning DENTAL IMPLANTS. "The aim was to evaluate the association between single-nucleotide polymorphisms (SNPs) in genes involved in inflammation and bone metabolism (BMP-4, BRINP3, CD14, FGF-3, FGF-10, GBP-1, IL-1α, IL-1β, IL-10, LTF, OPG, and RANKL) and peri-implantitis." (PMID 41373620, 2025).
prostate adenocarcinoma (2 papers, 2013 to 2018). "In addition, paracrine signaling of FGF10 promoted androgen independent survival of a subset of prostate adenocarcinoma, and also synergizes with epithelial autonomous AKT signaling, leading to high-grade carcinoma." (PMID 23900974, 2013).
renal agenesis (2 papers, 2010 to 2016). Renal agenesis (RA) is a form of renal tract malformation characterized by the complete absence of development of one or both kidneys (unilateral RA or bilateral RA respectively), accompanied by absent ureter(s). "Furthermore, although renal agenesis was rare in Fgf10 homozygotes (15%), removing one Gdnf allele (Fgf10−/−;Gdnf+/−) caused 100% agenesis." (PMID 20084103, 2010). "We found that removal of either one or both Fgf10 alleles resulted in 100% renal agenesis." (PMID 20084103, 2010). "If Fgf10 is also removed any remaining factors are insufficient to rescue kidney development, resulting in renal agenesis." (PMID 20084103, 2010). "Strikingly, renal agenesis could be avoided by treatment with fibroblast growth factor 10 (FGF10) or glial cell line-derived growth factor (GDNF), which restore levels of phospho-extracellular signal-regulated kinase (pERK)." (PMID 26315301, 2016). "Fgf10 heterozygotes always had normal ureters and kidneys, whereas Gdnf heterozygotes had a low frequency (7–10%) of defective UB outgrowth or renal agenesis." (PMID 20084103, 2010). "We found that FGF10, presumably signaling via FGFR2, is an essential component of this alternative signaling, as removing either one or two Fgf10 alleles in a Gdnf−/−;Spry1−/− background caused failure of UB emergence, leading to renal agenesis." (PMID 20084103, 2010). "Loss of Gdnf causes renal agenesis because in the presence of SPRY1 the level of FGF10 signaling via FGFR2 is not sufficient to produce the necessary responses, such as an appropriate level of Etv4 and Etv5 expression." (PMID 20084103, 2010). "When Spry1 is absent there is no brake on signaling via FGFR2, and GDNF can be removed without causing renal agenesis, due (at least in part) to the effects of FGF10, and to the restoration of Etv4/Etv5 expression; however, UB branching pattern is abnormal." (PMID 20084103, 2010).
sicca-syndrome (2 papers, 2008 to 2023). "A correlation of these FGF10 aberrations and sporadic cases of sicca-syndrome with symptoms identical to those of individuals with ALSG was excluded by screening DNA samples from 74 patients." (PMID 19102732, 2008). "FGF10 was injected into the LG of two mouse models of Sjögren's syndrome and healthy controls." (PMID 36715672, 2023).
silicosis (2 papers, 2021 to 2022). Silicosis is a respiratory disease caused by breathing in (inhaling) silica dust. "Further, the protein levels of MUC5AC and FGF10 detected by immunohistochemistry were significantly decreased in silicosis lungs, especially in epithelium." (PMID 34149803, 2021). "This analysis revealed both common and specific regulations in silicosis, along with several critical genes (e.g., MUC5AC and FGF10), which are potential drug targets for silicosis treatment." (PMID 34149803, 2021). "In our results, the pathway of lung epithelial progenitor cell differentiation, including several essential genes (e.g., FGF10, FGFR2), was remarkably down-regulated in silicosis, indicating disordered respiratory epithelium regeneration in the disease progression." (PMID 34149803, 2021).
Thyroid agenesis (2 papers, 2018 to 2020). "However, in view of the fact that for most patients with thyroid dysgenesis the causal mechanism is unknown, FGF10 and other factors associated with this signaling pathway are potentially new candidate genes worth exploring." (PMID 29361553, 2018). "To date, there are no reports linking thyroid dysgenesis, the most common cause of congenital hypothyroidism, to FGF10 mutations." (PMID 29361553, 2018). "By contrast, it has been reported that Fgf10-null mutant mouse embryos did not exhibit thyroid agenesis but rather severe hypoplasia (the thyroid was shaped normally)." (PMID 33381086, 2020).
ulcerative colitis (2 papers, 2019). An inflammatory bowel disease involving the mucosal surface of the large intestine and rectum. "Eighty-eight patients with a diagnostic of ulcerative colitis were enrolled in a clinical trial and received, for five consecutive days, either placebo or escalating doses of FGF10 (1, 5, 10, 25, and 50 μg/kg)." (PMID 31921841, 2019). "Repifermin (also called KGF2 or FGF10) was administered intravenously (IV) to patients with ulcerative colitis." (PMID 31921841, 2019).
acne (1 paper, 2021). An inflammatory process of the sebaceous glands which is characterized by comedones, nodules, papules and/or pustules on the skin. "Expression of FGFR2b-specific ligands FGF7 and FGF10 is androgen dependent, with androgen-induced upregulation of FGF10 being implicated in the pathogenesis of adolescent acne." (PMID 34007277, 2021).
acute myeloid leukemia (1 paper, 2023). Acute myeloid leukemia (AML) is a group of neoplasms arising from precursor cells committed to the myeloid cell-line differentiation. "Furthermore, FGF10/FGF17 has been identified as a prognostic and drug response marker in acute myeloid leukemia, suggesting that small-molecule inhibitors of FGF10 and FGF17 are promising therapeutic targets." (PMID 37108717, 2023).
adenoma (1 paper, 2015). A neoplasm arising from the epithelium. "Moreover, expression of key regulators of embryonic lung morphogenesis, Fgf9 and Fgf10, has been shown to trigger ADC and adenoma progression, respectively." (PMID 25713296, 2015).
Alagille syndrome (1 paper, 2026). "Cholangiocyte differentiation: activin A, retinoic acid, and FGF10 direct differentiation into cholangiocyte progenitors, critical for studying bile duct diseases such as Alagille syndrome and cholangiopathies." (PMID 41503024, 2026).
Anxiety (1 paper, 2023). Intense feelings of nervousness, tension, or panic often arise in response to interpersonal stresses. "In this study, we examined the effects of intranasal delivery of vehicle or FGF10 for 21 days on anxiety‐ and depression‐like behaviors in mice using the open field test." (PMID 37503695, 2023). "However, 3xTg‐vehicle mice spent less time in the center of the open field compared to wild‐type mice, while FGF10 treatment increased the time spent in the center, suggesting that FGF10 may alleviate anxiety‐ and depression‐like behaviors in 3xTg‐AD mice." (PMID 37503695, 2023).
atherosclerosis (1 paper, 2022). A disease characterized by the build-up of fatty material and calcium deposition in the arterial wall resulting in partial or complete occlusion of the arterial lumen. "V55 increased expression of Socs3 and Dab2 genes (inhibitors of cytokine signaling and NF-κB pathway), Apoe (associated to atherosclerosis control), Igf1 (encoder a protein with analogous effects to insulin) and Fgf10 (fibroblasts growth factor)." (PMID 35631379, 2022). "Moreover, (3S)-vestitol up-regulated the expression of Socs3 and Dab2 genes (inhibitors of cytokine signaling and the NF-κB pathway), Apoe (related to atherosclerosis control), Igf1 (encoder a protein with analogous effects to insulin) and Fgf10 (fibroblasts growth factor)." (PMID 35631379, 2022). "The (3S)-vestitol effect in reducing the expression of Scd1, Scd2, Egr1 and its impact on increasing the Apoe, Igf1, and Fgf10 expression demonstrates the positive effects that this molecule, derived from Brazilian red propolis, may have on metabolic diseases such as atherosclerosis and diabetes." (PMID 35631379, 2022).
athyreosis (1 paper, 2020). Athyreosis is a form of thyroid dysgenesis characterized by complete absence of thyroid tissue that results in primary congenital hypothyroidism, a permanent thyroid deficiency that is present from birth. "Mice deficient in Fgf10 or Fgfr2b exhibit athyreosis, indicating that Fgf10 is required for thyroid budding and branching morphogenesis." (PMID 33381086, 2020).
autoimmune disease (1 paper, 2021). A disorder resulting from loss of function or tissue destruction of an organ or multiple organs, arising from humoral or cellular immune responses of the individual to their own tissue constituents. "Studies regarding the role of FGF10 in inflammation have shown that FGF10 is overexpressed in psoriatic skin, which is an autoimmune disease." (PMID 34383782, 2021).
brain infarct (1 paper, 2016). "Administration of FGF10 into lateral cerebroventricle not only decreased MCAO-induced brain infarct volume and neurological deficit, but also reduced the number of TUNEL-positive cells and activities of Caspases." (PMID 26813160, 2016).
breast adenocarcinoma (1 paper, 2020). "Finally, in humans, FGF10 has been described to be expressed in 10% of the breast adenocarcinoma and activation of FGFR2b signaling correlates with a worse prognostic." (PMID 32676501, 2020).
bronchiolitis obliterans (1 paper, 2016). "Non-IPF control MSCs obtained from surveillance bronchoscopies and BAL from lung transplant recipients without bronchiolitis obliterans or infection showed significantly higher FGF-10 expression compared to IPF MSCs." (PMID 27869174, 2016).
Carpenter syndrome (1 paper, 2025). An extremely rare autosomal recessive syndrome characterized by premature closure of cranial sutures leading to cone-shaped head, fusion of the digits, and the presence of more digits than normal. "In RAB23-deficient mice, which mimic Carpenter syndrome in humans, the lack of functional RAB23 results in overt FGF10, Hh and Nodal signaling with consequent misexpression of downstream signal transducers (pERK1/2, Gli1, Lefty1/2 and Pitx2)." (PMID 40261407, 2025).
cognitive deficits (1 paper, 2023). "In our study, we utilized 3xTg‐AD mice, which are well‐established animal models that exhibit both amyloid and tau pathology, as well as cognitive deficits, to assess the potential therapeutic effect of FGF10 in vivo." (PMID 37503695, 2023).
colorectal tumors (1 paper, 2019). "The pattern of FGF-10 expression in tumor tissue based on pathological reports of the stage, grade, lymph invasion, site and size of colorectal tumors was evaluated." (PMID 31611737, 2019).
edema (1 paper, 2020). An abnormal accumulation of fluid beneath the skin, or in one or more cavities of the body. "It has also been suggested that FGF10 might have a potential therapeutic effect for lung edema due to its upregulating Na+/K+-ATPase activity in alveolar epithelial cells via the ERK1/2 pathway." (PMID 31958320, 2020).
endometriosis (1 paper, 2025). The growth of functional endometrial tissue in anatomic sites outside the uterine body. "The immunohistochemical analysis focused on the expression of IFN-τ, FGF-7, FGF-10, FGF-23, and HGF in both normal endometrial tissues and deep endometriosis samples." (PMID 40076699, 2025). "The findings demonstrated that FGF-7, FGF-10, and HGF exhibited significantly higher expression levels in the epithelium and stroma of normal controls compared to endometriosis samples." (PMID 40076699, 2025).
enophthalmos (1 paper, 2024). "Therefore, when HG formation is disturbed, the eye exhibits enophthalmos (the slit-eye phenotype), and a line of Fgf10+/− heterozygous loss-of-function mice exhibits slit-eye due to the HG atrophy." (PMID 38921483, 2024).